METTL3 (methyltransferase 3, N6-adenosine-methyltransferase complex catalytic subunit)
Diseases named in the same sentence as METTL3 in open-access papers (continued):
Sharing a sentence is not in itself a finding about the gene and the disease.
tumor (continued). "It has been confirmed that YTHDF2 induced the targeted degradation of the tumor suppressor SOCS2 to promote tumor progressions of HCC, and this regulation was dependent on METTL3-induced m6A modifications." (PMID 33121495, 2020). "Similar to the results of Li’s report, we found that KIAA1429, METTL3, and HNRNPC are highly expressed in HCC tumor samples." (PMID 32903675, 2020). "Comparing with the adjacent tissues, the writer (METTL3 and METLL14) expressions were upregulated in tumor tissues of LUAD patients, while the eraser FTO expression was downregulated." (PMID 32195181, 2020). "Both studies detected similar cellular phenotypes, i.e., METTL3 promoted the proliferation, self-renewal, invasion, and migration of OSCC cells in vitro, as well as tumor growth and metastasis in vivo." (PMID 32957697, 2020). "METTL3 regulates the expression of Integrin β1 (ITGB1) through m6A-HuR-dependent mechanism, which affects the binding of ITGB1 to Collagen I and tumor cell motility, so as to promote the bone metastasis of PCa." (PMID 33015074, 2020). "As core molecules of MTC, METTL3 and METTL14 often perform an opposite effect on tumor process in same cancer." (PMID 33159022, 2020). "The mean METTL3, GLUT1, HK2 immunohistochemical staining score in the tumor tissues was significantly higher than that in the peritumoral tissues (p < 0.001)." (PMID 32626532, 2020). "Next, we further estimated METTL3 and METTL14 expression in a larger cohort containing 136 paired tumor and paratumor tissues." (PMID 32175271, 2020). "Knockout of METTL3 dramatically reduced HCT116 tumor growth and tumor weight in xenograft mouse models." (PMID 32245489, 2020). "The overexpression of METTL3 promoted proliferation, invasion and migration of OSCC cells in vitro, whereas the METTL3 knockdown inhibited the tumor growth in vivo." (PMID 33375464, 2020). "METTL3 mRNA expression was significantly different between grade 2 and grade 3 in ESCA tumor grades (p = 0.003)." (PMID 32626532, 2020). "In the present study, the levels of METTL3 and CD33+ MDSCs were examined in tumour specimens from 197 patients with CC by IHC." (PMID 33059689, 2020). "In summary, we found m6A modification of AFF4 RNA was upregulated by METTL3 and their expression was elevated in BCSCs, which in turn promotes the expression of SOX2 and MYC to enhance tumorigenesis and tumor-initiating capacity of BCa." (PMID 32676121, 2020). "To understand the role of METTL3 in ESCA, we compared METTL3, GLUT1 and HK2 expression between tumor and matched normal tissue specimens from the 57 patients." (PMID 32626532, 2020). "In this study, we focused on the distribution of METTL3 and CD33+ MDSCs in the tumour microenvironment of 197 patients with CC." (PMID 33059689, 2020). "Downregulation of HK2 or SLC2A1 dramatically impaired METTL3-induced cell proliferation and colony formation in vitro and tumor growth in vivo, which further supported HK2 and SLC2A1 (GLUT1) as critical target genes of METTL3 in CRC." (PMID 32245489, 2020). "On the other hand, given that SUMOylation of METTL3 represses its m6A methyltransferase capacity and results in tumor growth of NSCLC, modification of m6A methylase can determine the tumor development." (PMID 31142332, 2019). "We found that upregulated METTL3 is responsible for abnormal m6A modification in CRC and correlates positively with tumor metastasis." (PMID 31492150, 2019). "MiRNA let-7g acted as a tumor suppressor and inhibited tumorigenesis by targeting the 3′ UTR of METTL3 mRNA." (PMID 31757221, 2019). "Interestingly, we found that the shared genes were the most enriched in the stem cell differentiation pathway through GO enrichment analysis on metascape website, indicating that this pathway might be regulated by METTL3 and promoted tumor metastasis via an m6A mechanism." (PMID 31230592, 2019).
tumor (continued). "Nevertheless, expression of METTL3 is reduced in endometrial carcinoma, which stimulates AKT signaling and promotes tumor growth and invasiveness both in vitro and in vivo." (PMID 31921664, 2019). "It remained unclear how upregulated METTL3 and downregulated METTL14 together participate in tumor development." (PMID 31492150, 2019). "To further assess the results, we obtained 60 paired tumor tissues and adjacent normal tissues of CRC, and qRT-PCR was used to determine the expression pattern of METTL3." (PMID 31492150, 2019). "Mechanistically, METTL3 promotes HCC growth and invasiveness by repressing the expression of suppressor of cytokine signaling 2 (SOCS2), a tumor suppressor in HCC, through m6A-YTHDF2-dependent mRNA degradation." (PMID 31921664, 2019). "Mettl3 normally methylates ADAM19 mRNA, resulting in the degradation of ADAM19 required for tumor suppression." (PMID 31798620, 2019). "Accordingly, silencing of METTL3 interrupts SOX2-dependent DNA repair, impairs GSC maintenance, and delays tumor propagation in vivo." (PMID 31921664, 2019). "Here, we identified METTL3 as a pivotal regulator in CRC, which promoted the development of tumor metastasis." (PMID 31492150, 2019). "Considering the accumulating evidence that ZNF217 plays an essential role in tumor progression, metastasis, and chemoresistance, it is predictable that ZNF217-regulated m6A modification, possibly by interaction with METTL3, is relevant in human cancers." (PMID 30149601, 2018). "It was shown that depletion of METTL3 restrained HCC growth and metastasis both in vitro and in vivo, but overexpression of METTL3 enhanced HCC cell proliferation and migration, as well as tumor growth in vivo." (PMID 30149601, 2018). "Mice grafted with the GSCs with KD of both METTL3 and METTL14 resulted in an increase in tumor progression that was even more dramatic than that seen in mice grafted with GSCs with METTL3 or METTL14 KD alone." (PMID 28297667, 2017). "Consistent with the aggressive tumor progression, mice grafted with PBT707 cells with KD of METTL3 or METTL14 alone or KD of both METTL3 and METTL14 had considerably worse survival outcomes than mice grafted with control GSCs." (PMID 28297667, 2017). "METTL3 mRNA and protein expression was lower in RCC samples compared with adjacent non-tumor samples, and lower in RCC cell lines (CAKI-1, CAKI-2 and ACHN) compared with HK-2." (PMID 29221190, 2017). "To further explore the function of METTL3 in RCC, we first validated the expression of METTL3 in RCC tissue samples and cell lines, indicating METTL3 expression was significantly lower in RCC samples compared with adjacent non-tumor samples." (PMID 29221190, 2017). "Targeting m6A writers (e.g., METTL3, METTL14), erasers (e.g., FTO, ALKBH5), or circRNA–miRNA interactions could restore regulatory balance and mitigate tumor aggressiveness." (PMID 41516402, 2026). "Therefore, inhibition of the METTL3/m6A axis, such as with small molecule peptides, decreases the stability of RRBP1 and blocks tumor progression." (PMID 41200062, 2026). "RNA methylation-targeting agents disrupt the survival of tumor cells by modulating three core components of the epitranscriptomic machinery that include demethylases (FTO), methyltransferases (METTL3, PRMT5) and oligonucleotide-based regulators of methylation enzymes." (PMID 41362736, 2026). "In NAFLD-HCC, targeting METTL3 with single-stranded RNA, nanoparticle siRNA, or drug inhibitors (STM2457) in combination with anti-PD-1 agents can synergistically activate cytotoxic CD8+ T cells and mediate tumor regression." (PMID 41362736, 2026). "Methyltransferase-like 3 (METTL3) regulates tumor metabolic reprogramming by controlling the expression of glucose transporters (GLUTs), lactate dehydrogenase (LDHA), and enolase 1 (ENO1) in tumor cells." (PMID 40046061, 2025).
tumor (continued). "Therefore, inhibiting methyltransferase activity like METTL3 or activating demethylases like FTO or ALKBH5 can reduce m6A modification levels, thereby inhibiting tumor progression and resistance." (PMID 40740874, 2025). "METTL3-mediated m6A modification upregulates TUG1, promoting tumor immune evasion." (PMID 40352941, 2025). "Besides, inhibitors such as RM3 and UZH2 suppress tumor progression in melanoma, AML, and prostate cancer (PCa) by targeting the METTL3/METTL14 complex and reducing m6A modification levels." (PMID 41446042, 2025). "Additionally, CAF-derived VEGFA upregulates METTL3 in NSCLC cells and activates the AKT/NF-κB pathway via RAC3, further promoting m6A methylation and enhancing tumor migration and invasion." (PMID 40740874, 2025). "In the TME, lactate-induced lactylation of METTL3 at K281 and K345 within its zinc-finger domain (ZFD) strengthens its affinity for m6A-modified RNAs, promoting m6A-mediated immunosuppression and ultimately facilitating tumor immune evasion." (PMID 40859309, 2025). "Here, we provided evidence that Mettl3 promotes the progression of ovarian, breast and testicle cancers by enhancing the Pfkfb3/lactate/H3K18la/PD-L1 axis, and PLGA-encapsulated Levosimendan synergistically reduces tumor size in combination with CDDP." (PMID 40765834, 2025). "TUG1, upregulated by METTL3-mediated m6A, regulates PD-L1 and CD47 by sponging miR-141/miR-340 and interacting with YBX1; its knockdown inhibits tumor growth, enhances CD8+T/M1 macrophage infiltration, activates CD8+T via PD-L1, and boosts macrophage phagocytosis through CD47." (PMID 40352941, 2025). "In vivo, it may inhibit tumour growth through the exosomal METTL3‐m6A‐ARF6 axis, potentially reducing the growth of tumours resistant to DDP." (PMID 40916076, 2025). "Strikingly, Mettl3-mediated m6A modification destabilized Smad3 mRNA via Ythdf2-dependent recognition of a specific m6A site (position 4591) in the 3’UTR, accounting for impaired tumor MDSC maturation." (PMID 41360769, 2025). "Firstly, the biological effects of m6A regulators such as METTL3 and METTL14 vary significantly across different cancer types, as these enzymes may promote tumor progression in one context while acting as tumor suppressors in another." (PMID 40734692, 2025). "Additionally, TRIM21-mediated METTL3 degradation induces ferroptosis by disrupting SLC7A11 mRNA stability and inhibits tumor progression during anti–PD-1 therapy." (PMID 40175350, 2025). "In fact, some factors, such as IL-6 and lactic acid, significantly promotion in the expression of Mettl3 in tumor MO-MDSC (data not shown)." (PMID 41360769, 2025). "CAFs deliver METTL3 to NSCLC cells, upregulating SLC7A5 expression, modulating tumor cell behavior." (PMID 40740874, 2025). "Mechanistically, METTL3 enhances the translation efficiency of Jak1 mRNA through m6A modification, thereby activating the JAK1-STAT3 signaling pathway and facilitating the formation of an immunosuppressive tumor microenvironment." (PMID 40567896, 2025). "METTL3 and METTL14 work together as a tumor suppressor in endometrial carcinoma." (PMID 40483535, 2025). "Epigenetic modifiers such as KMT2D, BCOR, METTL3 and METTL14 were a limiting factor for uncontrolled cell proliferation in 3D spheroids, which may reveal the mechanism of how they function as tumor suppressors in human cancer." (PMID 38853928, 2025). "Targeting these regulatory proteins (such as METTL3 inhibitors STM2457 and FTO inhibitors FB23-2) can reverse resistance and enhance the efficacy of immune checkpoint blockade, providing a new approach to overcoming tumor immune resistance." (PMID 41584846, 2025). "METTL3 is overexpressed in GC tissues, enhancing FNTA translation through YTHDF1-dependent m6A modifications, maintaining KRAS membrane localization and continuously activating the MEK/ERK pathway, driving tumor progression and metastasis." (PMID 41584846, 2025).
tumor (continued). "The qRT-PCR assay was performed in GC tumor tissues with or without HP infection and METTL3 had a significantly higher expression level in HP-positive tumor tissues than HP-negative." (PMID 39744419, 2025). "In another study, targeting METTL3 using nanoparticle-siRNA or a METTL3-specific inhibitor (STM2457) in combination with anti-PD-1 therapy reactivated CD8+ T cells, restored IFN-γ+ production, and regressed the growth of orthotopic NAFLD-HCC tumours." (PMID 39718205, 2025). "HK2 can be directly mediated by the m6A modifiers METTL3, YTHDF1, IGF2BP2, FTO and ALKBH5 in colorectal cancer and cervical cancer, leading to increased glycolysis, upregulated aerobic respiration in mitochondria and tumor progression." (PMID 41373022, 2025). "For instance, inhibiting METTL3 or METTL14, which increase PD-L1 expression on tumor cells, could reduce immune escape and restore T-cell activity, thus enhancing the response to immune checkpoint blockade." (PMID 39911396, 2025). "Additionally, METTL3 can regulate the stability of HDGF mRNA through m6A methylation, promoting tumor growth and liver metastasis in GC." (PMID 41584846, 2025). "Despite significant progress in research, there are still many challenges in this field: the functional background of writers is dependent, and the same writer (such as METTL3, METTL14) can play completely opposite roles in different tumors or even within the same tumor." (PMID 41256854, 2025). "Furthermore, our results indicate that the METTL3/miR-146a-5p mediated oncogenic effect in OSCC is via direct targeting of SMAD4, a well-known tumor-suppressor gene, by miR-146a-5p." (PMID 40338154, 2025). "METTL3- and METTL16-mediated m6A modification stabilizes ZNNT1 in HCC, which enhances macrophage recruitment and polarization to M2 via the osteopontin (OPN)/S100A9 feedback loop, ultimately supporting immune evasion and tumor progression." (PMID 40034695, 2025). "By analyzing the role of the modification of mRNA and ncRNA in cancer progression, researchers confirmed strong participation, mostly regarding METTL3/METTL14 complex, FTO, and ALKBH5, in tumor cell proliferation, invasion, migration, angiogenesis, metastasis, and drug resistance development." (PMID 41157107, 2025). "METTL3-mediated m6A methylation increases ADAR1 protein levels, promoting tumor growth." (PMID 40852728, 2025). "Moreover, METTL3-mediated stabilization of FMOD mRNA via increased m6A modification levels leads to elevated expression of pro-angiogenic factors, further driving tumor vascularization." (PMID 40740874, 2025). "To evaluate the effect of METTL3 O-GlcNAcylation on HCC tumorigenesis in vivo, we performed xenograft experiments in nude mice, which showed that METTL3 depletion significantly hindered HCC growth, as indicated by decreased tumor volume, weight, and proliferating cell nuclear antigen IHC." (PMID 40651967, 2025). "Mettl3 was highly expressed in MO-MDSC and was responsible for impeding tumor MDSC maturation." (PMID 41360769, 2025). "In CRC, METTL3-mediated m6A modification of GLUT1 mRNA enhances its translational efficiency, leading to increased glucose uptake, lactate production, and mTORC1 signaling activation, thereby driving tumor growth." (PMID 40859309, 2025). "In addition to RBM15, several other m6A methyltransferases, including METTL3, METTL14, and WTAP, play critical roles in tumor immunity by modulating RNA methylation and downstream immune responses." (PMID 41403702, 2025). "β-emolene could directly inhibit the expression of METTL3 and lead to the downregulation of autophagy-related proteins LC3B, ATG5, and ATG7, thereby inhibiting autophagy, tumor cell proliferation, and promoting cell apoptosis." (PMID 40830264, 2025).
tumor (continued). "In the MC38 allograft mouse model, knockout of METTL3 in tumor cells or treatment with STM2457, a highly potent and selective inhibitor of METTL3, synergistically enhances the efficacy of anti-PD-1 therapy, significantly reducing MDSC infiltration and increasing CD8 + T cell infiltration." (PMID 39987091, 2025). "In addition, the upregulation of METTL3 stabilizes HDGF mRNA through increased m6A modifications, enhancing tumor proliferation, metastasis and resistance to targeted drugs." (PMID 41584846, 2025). "First, target validation should integrate single-cell RNA-seq and spatial transcriptomics to map the expression of the enzyme (e.g. METTL3, ADAR1) across tumor and immune subsets within the tumor microenvironment (TME), ensuring tumor-specificity and identifying immune cell vulnerabilities." (PMID 40176140, 2025). "Moreover, the protein levels of METTL3 and TRIB3 were significantly suppressed in Tan-IIA treatment group-derived tumor samples compared to those from the control group." (PMID 39910904, 2025). "Furthermore, we demonstrated that METTL3 and METTL14 function as tumour suppressors by facilitating the maturation of miR‐146a‐5p, which in turn inhibited the migration and invasion abilities of GBC cells both in vitro and in vivo." (PMID 40785027, 2025). "Moreover, the overall m6A level and its related METTL3, METTL14, and WTAP protein levels, as well as cytoplasmic MALAT1-exporting IGF2BP3 and its distribution in xenograft tumor tissues, were increased in the HBx group." (PMID 40860202, 2025). "Immunohistochemistry staining (IHC) for patient liver specimens further confirmed the markedly higher METTL3 expression in tumor tissues than matched nontumor tissues." (PMID 40103332, 2025). "Our results demonstrated significantly higher METTL3 gene expression in tumor tissues, both in responders and non-responders, compared to normal control cells." (PMID 40736702, 2025). "Whether METTL3 and METTL14 play a tumorigenic or tumor-suppressor role in cancer remains controversial and inconsistent across various studies." (PMID 39103890, 2024). "Understanding how METTL3 regulates the expression of pro-angiogenic factors, such as VEGF, HIF-1α, and angiopoietins, within the tumor microenvironment could provide new strategies for anti-angiogenic cancer therapies." (PMID 39834386, 2024). "Conversely, METTL3 knockdown did not significantly alter the anti-tumor effects of T cells, regardless of atezolizumab treatment." (PMID 39720723, 2024). "METTL3 deletion abates m6A modification on Irakm mRNA and slows down its degradation, resulting in the increase of Irakm expression, which ultimately inhibits TLR signal-mediated macrophage activation and promotes tumor growth." (PMID 39403369, 2024). "Additionally, Pan and colleagues showed that the m6A writer METTL3 triggers the m6A-SCAP-cholesterol pathway, resulting in the suppression of anti-tumor CD8+ T cells, subsequently facilitating the development of MASLD-HCC." (PMID 38921460, 2024). "Besides, silencing METTL3/14 in TME affects the production of cytokines and chemokines, ultimately sensitizing tumor cells to interferon-γ treatment." (PMID 38711100, 2024). "Moreover, METTL3-mediated methylation of HINT2 mRNA at 3′ and 5′UTR regions, known for its tumor suppressor functions, facilitates the binding of YTHDF1 to promote its translation." (PMID 38444581, 2024). "METTL3 promotes the degradation of Irakm mRNA by adding m6A modification, enhancing TLR4 signaling, activating macrophages, and inducing M1 polarization in TAMs, thereby increasing their tumor-killing ability." (PMID 39372415, 2024). "RNA methylation could regulate the innate immunity of the body, and targeting these methylation regulatory molecules (such as METTL3, METTL4, and FTO) can directly enhance tumor immunotherapy." (PMID 38442004, 2024).